IL22 (interleukin 22)
Diseases named in the same sentence as IL22 in open-access papers (continued):
Sharing a sentence is not in itself a finding about the gene and the disease.
encephalitis (10 papers, 2012 to 2025). An acute inflammatory process affecting the brain parenchyma. "In a lethal West Nile virus (WNV) encephalitis mouse model, IL-22 deficiency resulted in reduced viral load, decreased inflammatory infiltration, and alleviated tissue pathology." (PMID 32843067, 2020). "Therefore, our results demonstrated a pathogenic role of IL-22 in ZIKV encephalitis of neonatal mice." (PMID 32843067, 2020). "However, in another study performed on mice pathogenic role of IL-22 is explicated where IL-22 signaling is reported to exacerbate lethal West Nile Virus (WNV) encephalitis prospectively due to WNV neuroinvasion." (PMID 33042126, 2020). "Specifically, in the case of West Nile virus, IL-22 is a key component in the formation and development of encephalitis by potentiating the neuroinflammatory process." (PMID 29311619, 2018). "It has been suggested that IL22 exacerbates lethal WNVNY99 encephalitis by promoting virus neuro invasion in mice." (PMID 27267361, 2016). "We report here that Il22−/− mice were more resistant to lethal West Nile virus (WNV) encephalitis, but had similar viral loads in the periphery compared to wild type (WT) mice." (PMID 22952908, 2012). "Together, our study indicates that IL-22 signaling may play a detrimental role in encephalitis in ZIKV-infected neonatal mice." (PMID 32843067, 2020). "In all, our study suggests that the neutralization of IL-22 may be a potential therapeutic against ZIKV encephalitis." (PMID 32843067, 2020). "In vitro, human brain microvasculature endothelial cells secrete CXCL1 and CXCL5 and favor transmigration of neutrophils under IL-22 stimulation, confirming that findings from animal experiments may apply to human encephalitis." (PMID 29678185, 2018). "However, whether IL-22 contributes to ZIKV-induced encephalitis and the underlying mechanisms is not entirely known." (PMID 32843067, 2020). "For example, in EV71 patients with encephalitis, IL-13 and IL-4 were the most increased cytokines, whereas in EV71 patients without encephalitis, IL-22 and macrophage inflammatory protein-1a (MIP-1a) were the most increased cytokines." (PMID 34079547, 2021). "In the mouse model of WNV encephalitis, the lack of IL-22 expression decreased CNS viral load, infiltration by neutrophils, and mortality rate, attenuating all the aspects of the intrathecal infection and inflammation." (PMID 29678185, 2018).
hepatitis C (10 papers, 2014 to 2024). "A study included 631 HCV patients found that IL-22 polymorphisms were involved in the progression of persistent hepatitis C virus infection." (PMID 25297677, 2014). "It has also been proven that high production of IL-22 is correlated with protective immune responses to hepatitis C." (PMID 36839448, 2023). "This inverse relationship of IL-22/IL-22BP regulating tissue damage has also been observed during Hepatitis C and schistosome infections." (PMID 26285207, 2015). "For hepatitis C, IL-22 mRNA and Th22 cell levels were elevated in the livers of patients with chronic hepatitis C (CHC) compared to controls, indicating that Th22 cells may be recruited to the liver by intrahepatic chemokines." (PMID 36839448, 2023). "They stated that the correlation between IL-22 and protective responses in vitro may not be available in vivo because physiological IL-22 levels in the liver cannot be accurately measured in vitro, which means that the exact role of IL-22 in hepatitis C remains controversial." (PMID 36839448, 2023).
ileitis (10 papers, 2011 to 2022). "We discovered that IL-33R/ST2 deficient mice have attenuated ileitis associated with increased IL-22 expression." (PMID 31057534, 2019). "Both ST2 and IL-33 are upregulated in the intestine and IL-33R/ST2 deficient mice have attenuated ileitis with increased IL-22 expression." (PMID 31057534, 2019). "Our group showed recently that in the small intestinal tract, however, IL-22 acts as a pro-inflammatory cytokine, given that acute Toxoplasma gondii induced ileitis was caused by IL-23p19 dependent IL-22 induction." (PMID 27322540, 2016). "In addition, ileal mucosa of IL-22 deficient mice was protected from the barrier defect seen in Toxoplasma gondii-induced ileitis in wild type mice shown by significantly higher Re values and correspondingly lower macromolecule fluxes." (PMID 33912578, 2021). "IL-22 neutralizing antibody administration converted resistance to ileitis of IL-33R/ST2 deficient mice to an inflammatory Th1 phenotype, which may be due to enhanced prostaglandin E2 production." (PMID 31057534, 2019). "Moreover, an enhanced Th17 response with elevated IL-17A and IL-22 expression has been reported upon T. gondii infection with diminished ileitis in IL-17RA and IL-22 deficient mice." (PMID 31057534, 2019). "Our results also implies a MIF-dependent pathogenic role of IL-22 in T. gondii-induced ileitis." (PMID 21977228, 2011). "It was previously shown that IL-22 can upregulate IL-18 production from intestinal epithelial tissues to enhance immune cell IFNγ production in T. gondii-induced ileitis." (PMID 36361787, 2022). "Although we have clearly detected elevated IFN-β upon IL-22 stimulation in vivo in the spontaneous ileitis in Atg16l1ΔIEC/Xbp1ΔIEC mice, the exact role of autocrine IFN-I hence remains to be elucidated." (PMID 30254094, 2018). "Whereas in the small intestines IL-22 exerts pro-inflammatory properties as shown in murine Toxoplasma gondii induced ileitis, IL-22 has anti-inflammatory functions in the colon." (PMID 28127403, 2017). "We next assessed the contribution of IFN-I signals to the IL-22–driven ileitis in Atg16l1ΔIEC mice." (PMID 30254094, 2018). "Thus, sustained IL-22 and IL-18 production promoted intestinal inflammation in the high dose oral infection model, as IL-22-/- and IL-18-/- mice exhibited significantly less infection-induced ileitis." (PMID 34938670, 2021). "Therefore, the beneficial effect of IL-22 administration on toxoplasma-induced ileitis may be relevant for human IBD of different origins." (PMID 31057534, 2019). "In conclusion, severe lethal ileitis induced by oral T. gondii infection is attenuated by blockade of ST2 signaling and may be mediated in part by endogenous IL-22." (PMID 31057534, 2019).
joint disease (10 papers, 2013 to 2024). "There is early evidence for changes in methylation levels of some genes in patients with skin and joint disease and in patients with joint disease with IL22 being proposed as a possible germ line risk factor for PsA." (PMID 34485351, 2021). "DMRs associated with joint disease (PsA vs. PsC probands) included the promoter and body of interleukin-22 (IL22), a cytokine produced by IL-23-driven Th17 cells, activated γδ T cells, CD8+ T cells, and monocytes, which was 10% hypermethylated in PsA probands." (PMID 30779748, 2019). "Changes in the methylation levels of genes associated with skin/joint disease (MBP, OSBPL5, SNORD115, and HCG26) and joint disease (IL22, ELF5, PPP2R2D, PTPRN2, and HCG26) were found." (PMID 33869291, 2021). "Despite a lack of association between baseline levels of the IL-23 effector cytokines IL-17A, IL-17F, and IL-22 with joint disease activity in the current analyses, improvements in this domain were observed through 2 years and correlated with baseline levels of acute phase proteins." (PMID 39493888, 2024). "In fact, IL-22 deletion increased the severity of the joint disease and damage, suggesting that in this setting IL-22 may have a protective function." (PMID 32427877, 2020). "Although few DMRs exceeded a 10% change in methylation, it is noteworthy that many of those which did play roles in the pathogenesis of skin disease (SIGLEC14, JAM3, PCOLCE, RXRB, ELF5, IL22), joint disease (MBP, HCG26, IL22, PPP2R2D, PTPRN2) or are known to be imprinted (OSBPL5, SNORD115)." (PMID 30779748, 2019). "The finding of IL22 as significantly hypermethylated in sperm of PsA compared to PsC probands and its significant correlation with methylation levels in the blood is particularly interesting given its role in inflammatory skin and joint disease." (PMID 30779748, 2019). "Biological inference prioritized notable DMRs associated with skin disease (SIGLEC14, JAM3, PCOLCE, RXRB), skin and/or joint disease (MBP, OSBPL5, SNORD115, HCG26), and joint disease (IL22, ELF5, PPP2R2D, PTPRN2, HCG26)." (PMID 30779748, 2019). "Despite this limitation, we can recognize it as a pilot study, and it was able to demonstrate that FLS responded to IL-22 regardless of donor joint disease." (PMID 32756816, 2020). "Therefore, the increased proportion of cells making IL-22 alone (that is, without IL-17 or IFNγ) in Ps skin compared to joints was of particular interest, given that this has not previously been studied in patients with both skin and joint disease." (PMID 24286492, 2013). "By contrast, reductions in serum IL-17F, IL-22, and BD-2 levels with guselkumab correlated with improvements in PASI scores across timepoints assessed, but not in joint disease activity." (PMID 39493888, 2024).
liver cirrhosis (10 papers, 2012 to 2024). "SNPs of IL‐22 have been proven to be associated with many diseases, including childhood cerebral malaria, liver cirrhosis and cancer risk." (PMID 35808996, 2022). "In humans, levels of IL-22 are elevated in patients suffering from liver cirrhosis, and high levels of IL-22 are associated with a worsened prognosis." (PMID 33851257, 2021). "In the article, “The role of IL22 polymorphisms on liver cirrhosis in patients with hepatitis B virus: A case control study”, which appeared in Volume 98, Issue 44 of Medicine, the incorrect abstract appears in the article." (PMID 31804385, 2019). "Our data indicate that processes in the liver that lead to deterioration of liver cirrhosis and its sequelae are associated with an increase of IL-22." (PMID 22967278, 2012). "To investigate whether systemic IL-22 levels are associated with complications of liver cirrhosis, we compared liver cirrhosis-related complications between patients with IL-22 serum levels above or below the ULN of 18 pg/ml." (PMID 22967278, 2012). "Up-regulation of IL-22 might be associated with the underlying etiology of liver cirrhosis." (PMID 22967278, 2012). "Serum levels of IL-22 in patients with compensated or stable decompensated liver cirrhosis are similar to those in healthy controls, but increase significantly in patients with acute decompensation of liver cirrhosis and acute-on-chronic liver failure (ACLF)." (PMID 34514001, 2021). "The corresponding mean levels of serum IL-22 as detectable by ELISA were 10-fold higher in patients with liver cirrhosis than in healthy donors (44.1 ± 68.4 and 4.6 ± 6.8 pg/ml)." (PMID 22967278, 2012). "Systemic IL-22 levels in patients with liver cirrhosis significantly correlated with the MELD score, substantiating that IL-22 is associated with deterioration of liver function and subsequent mortality of cirrhotic patients." (PMID 22967278, 2012). "As IL-22 serum levels were associated with mortality of patients with liver cirrhosis, we investigated the relation between the MELD score and IL-22 serum levels." (PMID 22967278, 2012). "According to this ULN, 57 out of 120 (47.5%) patients with liver cirrhosis but only 2 out of 40 (5.0%) healthy donors displayed elevated IL-22 serum levels." (PMID 22967278, 2012). "In contrast to the surrogate parameters currently used for the assessment of the prognosis of liver cirrhosis, IL-22 likely plays an active role in liver inflammation, regeneration and carcinogenesis." (PMID 22967278, 2012). "IL-22 positive cells were observed in 7 of 10 liver biopsies from patients with different etiologies of liver cirrhosis." (PMID 22967278, 2012). "To relate systemic IL-22 to the prognosis of clinical liver cirrhosis, we performed a prospective cohort study in which patients with advanced liver cirrhosis were consecutively enrolled and longitudinally followed." (PMID 22967278, 2012). "Elevated IL-22 levels were more frequent in patients with liver cirrhosis-related complications than in patients with compensated liver cirrhosis (60.0% vs. 17.1%, P < 0.001)." (PMID 22967278, 2012). "Our data show that, compared to healthy donors, IL-22 serum levels were significantly elevated in patients with liver cirrhosis." (PMID 22967278, 2012). "According to this threshold, 47.5% of patients with liver cirrhosis showed elevated IL-22 serum concentrations." (PMID 22967278, 2012). "This is a prospective cohort study including 120 liver cirrhosis patients and 40 healthy donors to analyze systemic levels of IL-22 in relation to survival and hepatic complications." (PMID 22967278, 2012). "With respect to the hepatoprotective effects of IL-22 in animal models, we assume that elevated IL-22 serum levels in liver cirrhosis still serve protective functions." (PMID 22967278, 2012).
liver cirrhosis (continued). "In patients with liver cirrhosis, elevated systemic IL-22 levels are predictive for reduced survival independently from age, liver-related complications, CRP, creatinine and the MELD score." (PMID 22967278, 2012). "IL-22 was detectable (>2.6 pg/ml) in 89 of 120 patients with liver cirrhosis, but only in 4 of 40 healthy controls (74.1% vs. 10.0%, P < 0.001)." (PMID 22967278, 2012). "Once again, a potential silver lining in the treatment of liver cirrhosis might lie within the protective effects of IL-22." (PMID 33851257, 2021). "Another report could correlate IL-22 serum levels of ALD patients with scores describing the extent of liver cirrhosis and damage." (PMID 33851257, 2021). "The role of IL-22 in disease progression of patients with liver cirrhosis is currently uncertain." (PMID 22967278, 2012). "The weak but significant inverse correlation between the ALT level and IL-22 serum level must be carefully interpreted, but may indicate that IL-22 has a hepatoprotective function in patients with advanced liver cirrhosis." (PMID 22967278, 2012). "Assuming that IL-22 possesses hepatoprotective properties in end-stage liver disease, IL-22 may be a relevant factor for progression of liver cirrhosis." (PMID 22967278, 2012). "Overproduction of IL-22 in liver cirrhosis may serve protective functions as indicated by murine models of disease; however, IL-22 beyond a certain threshold may also be pathogenic." (PMID 22967278, 2012). "The primary goal of this study was to investigate whether serum IL-22 relates to survival of patients with liver cirrhosis." (PMID 22967278, 2012). "Taking into account that IL-22 serum levels were stably increased in the majority of patients in the course of liver cirrhosis, the IL-22 serum level may be a valuable prognostic marker for long-term survival of patients with advanced liver cirrhosis." (PMID 22967278, 2012). "IL-22 may be particularly important for outcome of liver cirrhosis." (PMID 22967278, 2012). "Thus, processes that lead to a rise in systemic interleukin-22 may be relevant for prognosis of advanced liver cirrhosis." (PMID 22967278, 2012). "However, patients with elevated serum IL-22 (>18 pg/ml) levels showed reduced survival compared to those patients with normal IL-22 levels indicating that processes leading to deterioration of liver cirrhosis and its sequelae come along with an increase of serum IL-22." (PMID 22967278, 2012). "Thus, elevated levels of IL-22 as they are seen in liver cirrhosis could further increase the risk of suffering from an HCC in these patients, even if this cytokine might exert primarily protective effects during liver cirrhosis." (PMID 33851257, 2021). "IL-22 also correlated with CRP, a well-established surrogate marker of hepatic inflammation and prognosis of liver cirrhosis." (PMID 22967278, 2012). "Systematic analysis of serum IL-22 in relation to morbidity and mortality of patients with advanced liver cirrhosis has not been performed so far." (PMID 22967278, 2012). "We demonstrate herein that elevated systemic IL-22 levels are predictive for reduced survival in patients with liver cirrhosis independent of age, presence of liver-related complications, CRP, creatinine and the MELD score." (PMID 22967278, 2012). "Furthermore, IL-22+ immune cell frequency was also higher in HBV-infected patients with liver cirrhosis than in non-cirrhotic patients in positive correlation with cirrhotic stage score." (PMID 33042126, 2020). "To investigate whether IL-22 serum levels are associated with survival of patients with liver cirrhosis, we compared survival of patients with liver cirrhosis and normal IL-22 levels (below the ULN of 18 pg/ml) with survival of patients having elevated IL-22 serum levels (above the ULN of 18 pg/ml)." (PMID 22967278, 2012).
myocardial infarction (10 papers, 2012 to 2024). Gross necrosis of the myocardium, as a result of interruption of the blood supply to the area, as in coronary thrombosis. "Additional research with follow-up will be useful in understanding the role of IL-22 in patients with acute myocardial infarction who underwent PPCI." (PMID 39274184, 2024). "Th22 cells improve cardiac function post-myocardial infarction by producing IL-22, which inhibits leukocyte accumulation and modulates inflammation." (PMID 38879568, 2024). "Previous studies demonstrated that IL-22 protects against myocardial infarction by stimulating hepatic FGF21 expression." (PMID 37432218, 2023). "The plasma IL-22 level was significantly elevated in acute myocardial infarction (AMI) and unstable angina (UA) patients within 24 hours." (PMID 31011288, 2019). "Besides, circulating IL-22 levels are markedly higher in peripheral blood of patients with unstable angina and acute myocardial infarction (AMI) compared to stable angina and healthy control subjects." (PMID 34388961, 2021). "Thus, the therapeutic benefit of IL-22 may result from its ability to inhibit leukocyte accumulation, leading to improved cardiac function post-myocardial infarction in mice." (PMID 38879568, 2024). "Because IL-17, and possibly IL-22, secreted from inflammatory cells might affect cells of the immune system, we examined the expression of IL-17R and IL-22R on T cells and monocytes, cells presumably activated during myocardial infarction." (PMID 23202375, 2012).
pulmonary TB (10 papers, 2010 to 2023). "In mouse models and in humans with active pulmonary tuberculosis, both IL-17- and IL-22-producing CD4+ T cells and IL-17+γδ T cells were shown to contribute to the antimycobacterial immune response." (PMID 34054347, 2021). "In mouse models and in humans with active pulmonary tuberculosis, both IL-17- and IL-22-producing CD4+ T cells as well as IL-17+γδ T cells were shown to contribute to the antimycobacterial immune response." (PMID 34054347, 2021). "We previously reported significantly higher IL-22 levels in BAL fluid from patients with pulmonary TB, compared with healthy controls." (PMID 21767990, 2011). "We also observed increased IL-22 levels in BAL fluid from pulmonary TB patients, compared with healthy, M.tb infected controls." (PMID 21767990, 2011). "MTBs in pulmonary TB granulomas have been shown to recruit IL-22+ T cells." (PMID 36839448, 2023). "In addition, the bronchoalveolar lavage fluid (BALF) of pulmonary TB patients contains a large amount of IL-22 at significantly higher levels than the corresponding plasma." (PMID 36839448, 2023). "Compared to healthy people, CD4+ T cells producing IL-22 and IL-17A have been reported to be upregulated in BAL fluids of pulmonary TB patients, indicating their probable contribution to anti-mycobacterial responses." (PMID 30386336, 2018). "This is consistent with the report describing distinct IL-22 and IL-17 producing Th17 cells among CD4 T cells in active pulmonary TB patients." (PMID 20195465, 2010).